IL6R (interleukin 6 receptor)
Diseases named in the same sentence as IL6R in open-access papers (continued):
Sharing a sentence is not in itself a finding about the gene and the disease.
tumor (continued). "Cancer-associated adipocytes secrete the chemokines CCL2/5 and IL-6/TNF-α, which promote tumour proliferation and immune escape by binding to CXCR2 and IL-6R/TNF-R on the surface of tumour cells." (PMID 40414892, 2025). "Through IL-6R-mediated pathways, IL-6 has the potential to promote angiogenesis as well as tumor growth and progression." (PMID 39941858, 2025). "For instance, IL-6R inhibitors (e.g., Tocilizumab) combined with anti–PD-1 agents have demonstrated synergistic immune activation in desmoplastic tumor models." (PMID 41462920, 2025). "The finding that IL-6R is highly expressed in ALDHhigh ECSCs and that its inhibition significantly reduces tumor growth underscores the importance of inflammatory cytokine signaling in sustaining CSC properties." (PMID 41373619, 2025). "This analysis revealed an increased frequency of tumor-infiltrating monocytes and macrophages following IL-6R blockade, which was consistent with the flow cytometry data." (PMID 39653766, 2025). "Targeting the IL-6/IL-6R/ERK pathway emerges as a promising therapeutic approach for combating CAF-driven tumour progression and improving clinical outcomes in patients with aggressive, therapy-resistant HNSCC." (PMID 39858048, 2025). "Examining splenic and tumor-infiltrating lymphocytes, anti-IL-6R promoted the amounts of splenic CD4(+) helper T cells, CD8(+) CTLs and NK1.1(+) cells but not CD4(+)/CD25(+) Tregs as compared to isotype IgG treatment." (PMID 38505617, 2024). "Differently, both sequential immunotherapy (anti-PD-L1 → anti-IL-6R) and shMCT-1 treatment efficiently prevented postsurgical tumor metastasis to the lungs, particularly in combination of the sequential immunotherapy with shMCT-1 effect." (PMID 38505617, 2024). "Evidence for the role of IL6 and its cognate receptor (IL6R) within the tumour itself and surrounding microenvironment remains a key area of research." (PMID 39766336, 2024). "Surprisingly, in shMCT-1 circumstances, sequential immunotherapy (anti-PD-L1 → anti-IL-6R) successfully prevented tumor relapse (0%) and metastasis (28.5%), achieved a disease-free survival advantage (100%) and diminished the recurrent tumor loads." (PMID 38505617, 2024). "SW480 tumor cells with higher IL-6R expression levels showed better responsiveness in tocilizumab therapy than in the treated HT-29 group." (PMID 38256960, 2024). "Immunohistochemical staining of CRC tissue specimens from cohort 1 yielded a range of staining intensities for IL6R in the tumour cell cytoplasm, as shown by representative images." (PMID 39766336, 2024). "Our in vitro experiments furthermore showed that anti-IL-6R and CSF1Ri effectively prevent the development of tumor-induced CD14+ cDC2s." (PMID 38242119, 2024). "The tumor growth with anti-IL-6R antibody therapy further represented attenuated expressions of the mitotic index and Ki-67 staining." (PMID 38256960, 2024). "IL-6R ultimately promotes the expression of STAT3, forming a STAT3/miRNA/IL-6R feedback loop, promoting tumor cell invasion and migration." (PMID 38172648, 2024). "Despite their culture in the presence of tumor-associated factors from BLM-CM, cDC2s treated with anti-IL-6R and CSF1Ri even slightly outperformed untreated medium-cultured cDC2s." (PMID 38242119, 2024). "Conversely, in lung adenocarcinoma (n = 140), high IL6R protein expression predicted improved survival outcomes, and expression was higher in adjacent normal tissue compared to tumour epithelium." (PMID 39766336, 2024). "Signaling via its cognate IL-6 receptor (IL-6R) complex is critical in tumor progression and, therefore, IL-6R represents an important therapeutic target." (PMID 38715108, 2024). "In our TAME system, when CAFs were exposed to BCa cell-secreted GM-CSF, they subsequently upregulated the inflammation-associated genes IL-6, IL-6R, IL-8 and CXCL3, which support both tumor progression and CAF survival." (PMID 39199680, 2024).
tumor (continued). "An IL-6R blockade in conjunction with anti-PD-L1 antibodies in mice implanted with pancreatic cell lines has been shown to improve tumor control and to induce T cell infiltration." (PMID 38928238, 2024). "Targeting vCAFs or inhibit the IL‐6/IL‐6R axis in tumour cells would be an effective way to reduce the degree of malignancy." (PMID 38158643, 2024). "IL6R can be expressed within tumour cell membranes or can exist in a soluble state within the tumour cell cytoplasm." (PMID 39766336, 2024). "Postsurgical tumor relapse was also further inhibited by immunotherapy of IL-6R in the shMCT-1 group (12.5%) than in the scramble group (77.8%) when compared with IgG2b, κ treatment of scramble (100%) and shMCT-1 (55.6%) cohorts." (PMID 38505617, 2024). "Combination therapies, including anti-IL-6R and anti-PD-L1 immunotherapy, also showed promising results in reducing tumor growth and improving survival." (PMID 38689325, 2024). "Consistent with earlier research, these findings show that IL-6 regulates tumor formation and glucose metabolism via the IL-6R/STAT3 axis." (PMID 39060229, 2024). "High expression of IL6R in the tumour cell cytoplasm of cohort 2 also trended towards an association with reduced CSS in the full cohort (HR = 1.469, 95%CI; 0.968–2.228, p = 0.068)." (PMID 39766336, 2024). "In vivo administration of monoclonal anti-IL-6R neutralizing antibodies in tumor-bearing mouse models enhanced T cell responses and inhibited tumor growth." (PMID 39281678, 2024). "In SA region, the expression of CRP (P = 0.048), gp-130 (P < 0.001), JAK2 (P = 0.004), and IL-6 (P = 0.001) was lower in tumor tissues compared with normal tissues, while the expression of IL-6R (P = 0.191) and STAT3 (P = 0.960) was comparable." (PMID 38881895, 2024). "The tumor slices from the xenografts of these two cell lines showed different protein levels of IL-6R." (PMID 38256960, 2024). "The total intensity score of phosphor-Erk in the untreated SW480 tumor cells was approximately 60 via a semi-quantitative analysis, compared with 30 in the anti-IL-6R antibody-treated SW480 tumors." (PMID 38256960, 2024). "The results indicate that CRC tumor cells with higher IL-6R expression are more sensitive to anti-IL-6R antibody treatment." (PMID 38256960, 2024). "IL6high iCAF exhibited a distinct ligand expression involving IL6, which interacted with migratory tumor and M1/M2-like TAMs through IL6R, and HRH1 in endothelial cells to activate the inflammatory response and angiogenesis." (PMID 38892065, 2024). "MiR-155-5p in TAMs84 can activate the IL-6R/STAT3/miR-204-5p pathway in colorectal cancer (CRC) to induce tumor chemoresistance by regulating C/EBPβ." (PMID 38341519, 2024). "The macrophages preincubated with an anti‐IL‐6R antibody showed M1 polarization similar to those induced by the O‐glycan‐truncated tumor cells." (PMID 37452653, 2024). "Anti-PD-L1 showed the lowest tumor recurrence rate (15%) compared with anti-IL-6R (57%) and IgG 2b, κ (90%), but anti-IL-6R proved a better anti-metastasis outcome (31%) than anti-PD-L1 (44%) and IgG 2b, κ (50%)." (PMID 38505617, 2024). "Both IL‐6/IL‐6R blockade and O‐glycan truncation in tumor cells induced similar pro‐inflammatory phenotypes in macrophages and cytotoxic T lymphocytes (CTLs)." (PMID 37452653, 2024). "CRC cells advance as ADAM10 and ADAM17 cleave mMICA or membrane-bound IL-6R in the tumor microenvironment, and furthermore, the shedding of membrane-bound L1-CAM influences metastasis." (PMID 36572816, 2023). "In pre-clinical tumor models, IL6R blockade or genetic ablation of CTL-intrinsic IL-6 signaling synergized with anti-PD-L1 therapy to enhance anti-tumor CTL responses, leading to improved tumor control." (PMID 36599350, 2023). "They cause this effect through high expression of microvasculature signature genes and IL-6, along with their intimate interaction with ICC cells via the IL-6/IL-6R pathway, which in turn modulate tumor epigenetic alterations." (PMID 38239853, 2023).
tumor (continued). "It has been demonstrated that the IL6 blockade potentiates the anti-tumor effects of γ-secretase inhibitors in Notch3-expressing can be abrogated by the IL6R blocking antibody tocilizumab in breast cancer." (PMID 37898675, 2023). "In preclinical tumor models, blocking IL6R or gene ablation of intrinsic IL-6 signaling in CTLs, in combination with anti-PD-L1 therapy, enhances the anti-tumor CTL response, and improves tumor control." (PMID 37240834, 2023). "IL-6 acts directly at IL-6R located on tumor cells to induce the expression of STAT3 target genes, and then drive tumor proliferation, survival and drug resistance." (PMID 37404767, 2023). "HIF-1α and IL-6Rα overexpression in breast cancer patient sera creates a hypoxic environment and abnormal inflammation in tumor cells, promoting metastasis." (PMID 37658431, 2023). "Binding of that cytokine to its receptor (IL-6R) produces a set of complicated signals which were proven to be tumor enhancement." (PMID 37798688, 2023). "The IL-6 receptor (IL-6R) antagonist tocilizumab (Toc) was applied to verify the role of IL-6/IL-6R signaling during tumor cell migration and invasion." (PMID 36614179, 2023). "Only 74% of patients classified as high for tumour cell membrane IL6R were alive 5 years post‐surgery compared to 86% of patients classified as low for membrane IL6R." (PMID 37199043, 2023). "IL-6 is secreted by tumor cells to regulate tumorigenesis and progression in two ways: it binds to IL-6 receptors (IL-6R) on its own target cells through the autocrine pathway, and it acts on IL-6R on the surface of other cells through the paracrine pathway." (PMID 37576403, 2023). "MAP4K1 facilitates GBM cell proliferation, survival, and tumor growth by remodeling cytokine–chemokine signaling networks, including the IL-18R and IL-6R pathways." (PMID 37734869, 2023). "IL-6 activates the corresponding receptor IL-6R on tumour cells and CAFs by means of autocrine–paracrine, which leads to differential activation of the STAT3 and MEK/ERK signalling pathways, resulting in tumour development." (PMID 37927475, 2023). "Compared with either anti-IL6R or anti-PD-L1 monotherapy, combined blockade of IL6R and PD-L1 significantly improved tumor control and progression-free survival (HR = 0.11, p < 0.0001)." (PMID 36599350, 2023). "First, tumor cells have been observed to secrete high levels of IL-6, which upregulate the expression of the IL-6 receptor (IL-6R) in MSCs while enhancing their proliferation and migration towards the tumor both in vitro and in vivo." (PMID 36830980, 2023). "Scores for tumour membrane IL6R were available for 578 patients and ranged from 0 to 150 with a mean of 3.84." (PMID 37199043, 2023). "This XIST-driven production of IL-6 from ALDH− bulk tumor cells preferentially binds to IL6R on ALDH+ CSCs to drive STAT3 activation and expression of key CSC factors (i.e., c-MYC, KLF4 and SOX9), promoting self-renewal of ALDH+ CSCs." (PMID 36922677, 2023). "For example, L1CAM promoted STAT3 activation via the IL-6/IL-6Rα axis to regulate tumor angiogenesis and vessel stabilization." (PMID 37248458, 2023). "The CRISPR-selective deletion of the CRNDE reduces MM cells proliferation, adhesion, and tumor growth by downregulating the expression of IL-6R, hence preventing the activation of IL-6/IL-6R pathway, essential for MM pathogenesis and progression." (PMID 35454868, 2022). "Our results indicate that the combination of Stt + Tcz effectively and synergistically inhibits the IL-6/IL6R/STAT-3 pathway in tumor cells." (PMID 35465350, 2022). "Malignant cell clusters shared cancer characteristics and widely significantly overexpressed HLA-A, HLA-B, MCL1, HDAC1, LCK, HSPB1, and IL6R, indicating a common tumor origin." (PMID 36131282, 2022).
tumor (continued). "IL-6 signaling can be targeted in a variety of ways, including the use of anti-IL-6 (siltuximab) or IL-6R (tocilizumab) monoclonal antibodies, which have both been extensively studied in different experimental tumor models as well as in clinical trials." (PMID 36405719, 2022). "When inhibiting synthesis of human IL‐6 from PC cells by RNA silencing and inhibition of human IL‐6/gp130 axis by tocilizumab, anti‐IL‐6R antibody, the growth of tumor was suppressed in the N‐inv model." (PMID 35578571, 2022). "Under hypoxic conditions in an immunosuppressive TME, upregulation of IL-6R expression on tumour cells and increased IL-6 production have been reported, inducing M2-TAMs and further promoting tumour progression and expansion, and survival resistance." (PMID 36439165, 2022). "Targeting IL-6 or IL-6 receptor (IL-6R) for tumor immunotherapy to block MDSC-mediated immunosuppression in cancer patients." (PMID 36263056, 2022). "Rapid production of IL-6 contributes to host defense during infection and tissue injury, but excessive synthesis of IL-6 and dysregulation of IL-6R signalling is often involved in disease pathology such as tumour progression and metastasis." (PMID 34223877, 2021). "IL-6, produced by tumors or tumor-infiltrating cells, binds to its target receptor IL-6R and leads to Jak2/STAT3 activation." (PMID 34833950, 2021). "IL-6 crosstalk between tumour cells and GCAFs not only supports tumour growth, but also promotes CAFs activation through IL-6Rα." (PMID 33810350, 2021). "Accordingly, increased levels of soluble IL6R are observed in the lungs of tumor-bearing Gp130F/F;KrasG12D mice, and blocking this signaling pathway with an anti-IL6R antibody or the inhibitor sgp130Fc abrogates tumorigenesis in vivo." (PMID 34944848, 2021). "Silencing IL6R expression suppressed tumor growth, migration and angiogenesis, as well as enhanced the antitumor activity in several cancer cells." (PMID 33714953, 2021). "Studies in SCID mice implanted with WM cell lines which were treated with an anti-IL6R antibody, showed lower levels of IgM and a reduction of tumor growth." (PMID 33921415, 2021). "An emerging research field deals with the understanding of the tumor cell response to IL-6 taking into account the precise regulation of IL-6 receptor complex consisting of IL6-R and gp130 proteins, which also exists in membrane-bound and/or soluble forms." (PMID 34576335, 2021). "Studies on CD2F1 mice inoculated with C26 cells presented an increase in the production of IL-6, IL-6R, and F4/80 (a marker for macrophages infiltration) in the heart of tumor-bearing vs. non-tumor-bearing mice." (PMID 33557173, 2021). "To identify the sources of IL-6 and sIL6R, we measured Il6 and Il6r mRNA expression in muscle, fat, liver, and tumor." (PMID 33851955, 2021). "As expected, decreased levels of pSTAT3 and target genes were observed in anti-IL-6R-treated Apcmin/+Ripk3-/- mice and correlated positively with decreased tumor numbers." (PMID 33996591, 2021). "High levels of certain inflammatory cytokines like IL-6 in the tumor microenvironment can bind to membrane-bound receptor molecules (IL-6R) in tumor cells." (PMID 33980865, 2021). "In the case of the IL6R, the following numbers were denoted: intra-tumor lymphocytes 4/28, interphase zone lymphocytes: 7/28 and tumor cells: 11/28." (PMID 32621022, 2021). "To investigate the effect of IL-6 blocking on tumor growth in vivo, we administered tocilizumab (IL-6R antibody) and apigenin, individually or together with paclitaxel, to mice bearing PDX tumors." (PMID 34588424, 2021). "Our results showed that treatment with stromal IL6 increased genes involved in glucose metabolism, specifically glycolysis, that decreased when IL6 receptor on tumor cells was silenced by siRNA for IL6R in SU86.86." (PMID 33177492, 2020).
tumor (continued). "In breast cancer tumor xenografts, the combination of maraviroc and cMR16-1 (anti-murine IL-6R antibody) dramatically inhibited tumor growth and prevented thoracic metastasis, compared to the single agents." (PMID 32630699, 2020). "We further observed that the effect of IL6 was reverted upon silencing the IL6 receptor on tumor cells (by siRNA for IL6R) as well as upon inhibition of glucose transporters by STF31." (PMID 33177492, 2020). "The systematically positive effect of IL-6 on tumor survival must be accounted for: IL-6 binds to soluble IL-6R (sIL-6R), which interacts with gp130 on tumor cells." (PMID 32867390, 2020). "IL-6 stimulates tumour cell proliferation and survival through the inhibition of apoptosis and interference with IL-6R signalling leads to decreased UM cell viability." (PMID 33066024, 2020). "In many tumors, IL-6 and its receptor IL-6R are highly expressed, and the high expression of IL-6 is closely related to the poor clinical prognosis of tumor patients." (PMID 32549792, 2020). "Increased IL-6 levels have been observed in the serum and tumor microenvironment, and all immune cells (such as NK cells, effector T cells, and DCs) in the tumor microenvironment express IL-6R." (PMID 33363013, 2020). "Agents blocking IL-6/IL-6R or inhibiting JAK/STAT3 to block tumor progression have been or are being tested in clinical trials, such as siltuximab (an anti-IL-6 mAb), tocilizumab (an anti-IL-6R mAb), Ruxolitinib (a JAK signaling inhibitor)." (PMID 32039001, 2019). "Taken together, our findings identify IL-6Rα as a direct target of MH and its flavonoids, highlighting IL-6R blockade as a mechanism for the anti-tumor activity of MH, as well as a viable therapeutic target in IL-6-dependent cancers." (PMID 31491838, 2019). "microRNA-34a (miR-34a) has been shown to be a key regulator of tumor suppression by targeting several cancer-related signals, including the interleukin-6 receptor (IL-6R)/Signal Transducers and Activator of Transcription 3 (STAT3) signaling pathway." (PMID 31448054, 2019). "IL-6/IL-6R/gp130 pathway communicates between breast tumor and immune cells, resulting in tumor promotion and enriched effect on BCSCs." (PMID 30885232, 2019). "Tumor suppressor miR-34a was induced upon MCT-1 knockdown that inhibited IL-6R expression and activated M1 polarization." (PMID 30885232, 2019). "We next assessed the expression of both chains of the IL‐6R in tumor biopsies from a cohort of 114 DLBCL patients that were spotted on tissue microarrays." (PMID 31515941, 2019). "Treatment of the mice with a neutralizing antibody against IL-6R drastically reduced the tumor score." (PMID 31694340, 2019). "We administered maraviroc (8 mg/kg body weight, orally daily) and cMR16-1 (murine surrogate of the anti-IL-6R antibody, 10 mg/kg body weight, i.p., 3 days a week), and monitored tumor growth for 5 weeks." (PMID 29898755, 2018). "There are increased levels of IL-6R in SCC tumours, relative to OAC, yet a correlation between the IL-6R levels and pSTAT3 is detected in both of the histological subtypes." (PMID 29890775, 2018). "Recent evidence shows that IL-6R is overexpressed on CSCs and IL-6 secreted by both tumor cells and endothelial cells (ECs) enhances the survival, self-renewal and tumor initiation potential of cancer stem cells in HNSCC." (PMID 29351275, 2018). "Further, in a xenograft mouse model, we showed that tumor growth was dramatically inhibited by cMR16-1, the mouse version of the anti-IL6R antibody." (PMID 29898755, 2018). "We also used the model to predict tumor response to administration of the humanized IL-6R monoclonal antibody, tocilizumab (TCZ), as monotherapy." (PMID 29351275, 2018). "STAT3 antagonist JSI-124 suppressed both CD11b+Gr-1− e-MDSCs and conventional CD11b+Gr-1+ MDSCs simultaneously and induced considerable recovery of T cell immunity in vivo and in vitro, thereby displaying more significant anti-tumor efficiency than IL-6R Ab." (PMID 30083161, 2018).